NLRP3 (NLR family pyrin domain containing 3)
Diseases named in the same sentence as NLRP3 in open-access papers (continued):
Sharing a sentence is not in itself a finding about the gene and the disease.
Peritoneal Fibrosis (9 papers, 2019 to 2025). Disorder characterized by a wide range of structural changes in PERITONEUM, resulting from fibrogenic or inflammatory processes. "It has been shown that high glucose-based PD solution activates NLRP3/IL-1β peritoneal mesothelial cells and that genetic deficiency of NLRP3 complex or IL-1β reduces inflammatory and peritoneal fibrosis model in mice." (PMID 35563220, 2022). "MGO induced parietal and visceral peritoneal fibrosis in wild-type mice, which was significantly reduced in mice deficient in NLRP3, ASC, and interleukin-1β (IL-1β)." (PMID 31316105, 2019). "Furthermore, fluoxetine has been observed to inhibit NLRP3, a protein implicated in peritoneal fibrosis-related inflammation." (PMID 40507495, 2025). "Also, peritoneal fibrosis evoked by methyl-glyoxal (MGO) delivery was attenuated in ASC deficient mice (an adaptor molecule downstream NLRP3), and reduced macrophage infiltration was observed." (PMID 38842647, 2024). "Using human and murine primary vascular endothelial cells, we showed that MGO markedly induces cell death through ROS generation, which is prevented by ASC deficiency, suggesting that endothelial NLRP3 inflammasome contributes to the process of PD-related peritoneal fibrosis." (PMID 31316105, 2019). "The present findings showed that endothelial NLRP3 inflammasome contributes to peritoneal inflammatory and fibrotic responses in the pathophysiology of PD-related peritoneal fibrosis, and provide new insights into the mechanisms underlying the pathogenesis of this disorder." (PMID 31316105, 2019). "The present results indicate that NLRP3 inflammasome plays a crucial role in inflammatory and fibrotic responses in the development of PD-related peritoneal fibrosis, and provide new insights into the mechanism underlying the pathogenesis of PD-related peritoneal fibrosis." (PMID 31316105, 2019). "Treatment with ONO-AE3-208 significantly prevented peritoneal inflammation and peritoneal fibrosis by inhibiting activation of the NLRP3 inflammasome and reducing phosphorylation of NF-κB." (PMID 36438844, 2022). "Our previous study showed that mPGES-1 contributed to peritoneal fibrosis by activating the NLRP3 inflammasome; thus, in this study, we examined the effects of ONO-AE3-208 on NLRP3 inflammasome activation." (PMID 36438844, 2022). "In the present study, we further demonstrated that an EP4 antagonist attenuated peritoneal fibrosis by inhibiting activation of the NLRP3 inflammasome." (PMID 36438844, 2022). "In conclusion, an EP4 antagonist reduced the development of peritoneal fibrosis, possibly by suppressing NLRP3 inflammasome- and p-p65–mediated inflammatory responses." (PMID 36438844, 2022). "In this research work, we did not investigate the contribution of prostaglandin E2 receptors during the NLRP3 inflammasome activation and peritoneal fibrosis." (PMID 34084773, 2021). "Here, we investigated the role of NLRP3 inflammasome in a murine model of PD-related peritoneal fibrosis induced by methylglyoxal (MGO)." (PMID 31316105, 2019). "In the present study, we used mice deficient in NLRP3, ASC, and IL-1β, and generated MGO-induced peritoneal fibrosis, which is an excellent murine model for human PD-related peritoneal fibrosis." (PMID 31316105, 2019). "We clearly showed that deficiency of NLRP3, ASC, or IL-1β reduced inflammatory and fibrotic responses in a MGO-induced peritoneal fibrosis model." (PMID 31316105, 2019). "Furthermore, the EP4 antagonist significantly reduces peritoneal fibrosis and improves dysfunction by inhibiting NLRP3 inflammasome and p-p65-mediated inflammatory responses." (PMID 40666730, 2025). "The results of our previous study showed that mPGES-1 promoted the synthesis of extracellular matrix protein via activation of the NLRP3 inflammasome in RPMCs exposed to high levels of glucose, indicating that the NLRP3 inflammasome participated in peritoneal fibrosis." (PMID 36438844, 2022).
Peritoneal Fibrosis (continued). "Thus, further studies are needed to elucidate the precise mechanism and role of NLRP3 inflammasome in PD-related peritoneal fibrosis." (PMID 31316105, 2019). "In the present study, we showed that deficiency of NLRP3, ASC, and IL-1β attenuates inflammatory and fibrotic responses after MGO treatment, resulting in less peritoneal fibrosis in a murine model of PD-related peritoneal fibrosis and EPS." (PMID 31316105, 2019). "Moreover, because the NLRP3 inflammasome is thought to play a role mainly in inflammatory cells, we assessed MGO-induced peritoneal fibrosis in myeloid cell-specific ASC-deficient mice." (PMID 31316105, 2019). "However, the role of NLRP3 inflammasome in PD-related peritoneal fibrosis remains to be elucidated." (PMID 31316105, 2019). "First, although we showed that NLRP3 deficiency significantly attenuates MGO-induced peritoneal fibrosis, we have not examined whether deficiency of other inflammasome-forming PRRs, such as NLRP1, NLRC4, and AIM2, could inhibit peritoneal fibrosis." (PMID 31316105, 2019). "In conclusion, the present study demonstrates that NLRP3 inflammasome triggers vascular endothelial cell damage and subsequent peritoneal inflammatory and fibrotic responses, resulting in MGO-induced peritoneal fibrosis." (PMID 31316105, 2019).
retinal ischemia (9 papers, 2015 to 2023). A ischemic disease that involves the retina. "Evidence suggests that cerebral and retinal ischemia share acute and chronic pathogenic mechanisms including NLRP3 inflammasome activation, which has been shown to be associated with injury severity." (PMID 34305534, 2021). "In our study, Bip and CHOP proteins as markers of ER stress changed accordingly with the regulation of Homer1 in this experiment, verifying the role of ER stress in the TXNIP/NLRP3-mediated pyroptosis-signaling pathway after MCAO-induced retinal ischemia." (PMID 38069134, 2023). "In this study, it was demonstrated that TXNIP/NLRP3-mediated pyroptosis also played an important role after retinal ischemia." (PMID 38069134, 2023). "Although it was found in this study that Homer1 can regulate ER stress-related TXNIP/NLRP3-mediated pyroptosis through the AMPK signaling pathway in the MCAO–retinal ischemia model, some limitations cannot be ignored." (PMID 38069134, 2023). "It was shown that TXNIP/NLRP3-mediated pyroptosis was located predominantly in RGCs, which gradually increased after retinal ischemia and peaked at 24 h after retinal ischemia." (PMID 38069134, 2023). "In the present work, we found that inhibition of caspase-8 activation resulted in significant depletion of NLRP3, an observation that agrees with other work indicating a role for caspase-8 in intraocular pressure-induced retinal ischemia." (PMID 33531049, 2021). "Several papers have reported that caspase-8 activates NLRP3 in human monocytes, intraocular pressure-induced retinal ischemia, and after chemotherapeutic treatment." (PMID 33531049, 2021). "Our previous study has demonstrated that NLRP3 level is elevated in retinal tissue damage following retinal ischemia." (PMID 32295623, 2020). "Several reports have demonstrated that the activation of NLRP3 inflammasome is drawn into the inflammatory injury of retinal ischemia." (PMID 29502235, 2018). "Several reports have demonstrated that inflammation participated in the pathogenesis of ocular NV and the NLRP3 inflammasome activation was involved in the inflammatory injury of retinal ischemia." (PMID 29502235, 2018). "We previously demonstrated that TLR4 promoted the activation of NLRP3 inflammasome which involves in the inflammatory injury of retinal ischemia." (PMID 26224068, 2015). "In conclusion, it was suggested that Homer1 may protect against MCAO-induced retinal ischemia and RGCs pyroptosis by inhibiting endoplasmic reticulum stress-associated TXNIP/NLRP3 inflammasome activation after MCAO-induced retinal ischemia." (PMID 38069134, 2023). "Besides, PPARγ also controls the NF-κB-dependent NLRP3 priming in different contexts including astrocytes and retinal ischemia/reperfusion." (PMID 33716981, 2021). "Furthermore, we have also reported that caspase-8 (CASP8)-induced NLRP3 promotes IL-1β processing during innate immune responses in an IOP-induced retinal ischemia model." (PMID 32295623, 2020). "The NLR pyrin domain containing 3 (NLRP3) inflammasome is an important activator of inflammation, which may play a critical role in catalyzing and forming certain pro-inflammatory cytokines in both cerebral and retinal ischemia." (PMID 34305534, 2021). "A recent study showed that inhibition of caspase-1 reduced IL-1β expression to baseline post retinal ischemia injury, while inhibition of caspase-8 further down-regulated the level of IL-1β, suggesting that IL levels could be regulated by both NLRP3-dependent and other pathways." (PMID 26893104, 2016). "In the present study, it was shown that TXNIP/NLRP3-mediated pyroptosis increased gradually and peaked 24 h after MCAO-induced retinal ischemia." (PMID 38069134, 2023). "Given these novel findings, we have determined that IL-1β is a central factor enhancing CASP8-HIF-1α signaling to subsequently increase NLRP3/NLRP12/NLRC4 activation and to initiate pyroptosis during retinal ischemia." (PMID 32295623, 2020).
retinal ischemia (continued). "Together, these findings depict a novel function for NLRP12 in pyroptosis with regard to the pathogenesis of retinal ischemia and RGCs death, indicating that NLRP12 coordinates with NLRP3 and NLRC4 to exert both neuroinflammatory and pyroptotic effects under ischemic conditions." (PMID 32295623, 2020).
septic shock (9 papers, 2018 to 2024). Shock caused by infection; frequently caused by gram negative bacteria, although some cases have been caused by other bacteria, viruses, fungi, and protozoa; characterized by fever, chills, tachycardia, tachypnea, and hypotension. "Using samples from four septic shock patients, we showed that this technique allows for the detection of NLRP3 inflammasome exhaustion in clinical samples." (PMID 36291172, 2022). "It was reported that LPS-induced septic shock is NLRP3 inflammasome dependent, and the inhibition of its activation could mitigate septic shock." (PMID 30291237, 2018). "Our study confirmed that septic shock induced myocardial pyroptosis through NLRP3 inflammasome/Caspase-1/GSDMD pathway, and inhibition of pyroptosis was found to alleviate septic shock-induced cardiac dysfunction." (PMID 36992838, 2023). "Moreover, Nlrp3+/+ mice injected with LPS displayed a mild systemic inflammatory response characterized by increased concentrations of specific chemokines and cytokines, including IL-1α and TNF, the latter being the prime mediator of the inflammatory response observed in septic shock." (PMID 35993366, 2022).
vascular dementia (9 papers, 2021 to 2025). A degenerative vascular disorder affecting the brain. "Investigating the activation of the NLRP3 inflammasome can reveal the pathogenesis of vascular dementia from a new perspective and propose innovative preventive and treatment strategies." (PMID 40326096, 2025). "Concurrently, there is evidence suggesting that aberrant NLRP3 inflammasome activation directly mediates neuronal and hippocampal cell pyroptosis, contributing significantly to vascular dementia pathogenesis." (PMID 40963935, 2025).
acute lymphoblastic leukemia (8 papers, 2019 to 2025). Leukemia with an acute onset, characterized by the presence of lymphoblasts in the bone marrow and the peripheral blood. "The promoter region of NLRP3 was examined as hypomethylation of this region is known to affect gene expression and cause steroid resistance in acute lymphoblastic leukaemia." (PMID 36831050, 2023). "Remarkable results were obtained in a study regarding the NLRP3 inflammasome’s contribution to acute lymphoblastic leukemia (ALL) in pediatric patients." (PMID 35897704, 2022). "Moreover, studies have reported that NLRP3 inflammasome activation may be associated with a poor prognosis in acute lymphoblastic leukemia (ALL) patients." (PMID 34801085, 2021). "For instance, the NLRP3/Caspase1 complex is able to cleave GR, thus impairing glucocorticoid activity in acute lymphoblastic leukemia (ALL) patients." (PMID 33716981, 2021). "However, how NLRP3 inflammasome contributes to the pathogenesis and clinical features of acute lymphoblastic leukemia (ALL) is still unknown." (PMID 31428046, 2019).
acute monocytic leukemia (8 papers, 2015 to 2023). Acute monoblastic leukemia (AML-M5), is one of the most common subtypes of acute myeloid leukemia (AML) that is either comprised of more than 80% of monoblasts (AML-M5a) or 30-80% monoblasts with (pro)monocytic differentiation (AML-M5b). "Owing to the difficulties in collecting human primary monocytes, the THP-1 monocyte-like cell line, derived from acute monocytic leukemia, has been extensively used in the study of NLRP3 inflammasome biology, despite its tumoral origin." (PMID 34576117, 2021). "To test whether ethyl pyruvate prevents NLRP3 agonists-triggered mitochondrial damage, we directly assessed mitochondrial integrity in human acute monocytic leukemia cell lines (THP-1) using electron microscopy (EM)." (PMID 30134814, 2018). "SeV infection induces the activation of MAVS signaling by promoting NLRP3-dependent caspase-1 activation, whereas knockdown of MAVS expression significantly attenuated the NLRP3 inflammasome in human acute monocytic leukemia cells (THP-1) and mouse macrophages." (PMID 36560803, 2022).
apical periodontitis (8 papers, 2019 to 2026). "In addition, estrogen deficiency can induce activation of the NLRP3/caspase-1/IL-1β axis and aggravate periapical bone loss in postmenopausal patients and ovariectomized rats with periapical periodontitis." (PMID 34177950, 2021). "Increased IL-1β production in periapical periodontitis may be associated with the activation of NLRP3 and AIM2 inflammasomes." (PMID 34177950, 2021). "Reports indicate that NLRP3 plays a crucial role in the development and regulation of apical periodontitis." (PMID 40909264, 2025). "Candida albicans, another species that is frequently isolated from endodontic infections of periapical periodontitis, was shown to induce pyroptosis by activating the NLRP3 inflammasome in mononuclear phagocytes and macrophages." (PMID 34177950, 2021). "For instance, lipoteichoic acid from Enterococcus faecalis, the most common pathogen in periapical periodontitis, can induce the expression of NLRP3 and increase the levels of caspase-1 and IL-1β, thus resulting in bone loss." (PMID 34869060, 2021). "NLRP3 plays key roles in the pathogenesis of periapical periodontitis, and F. nucleatum is one of the crucial microorganisms that might activate the inflammasome in periapical tissues." (PMID 31993418, 2019). "Notably, NLRP3 and NFE2L2 have previously been associated with apical periodontitis." (PMID 40909264, 2025). "Collectively, canonical inflammasomes, such as NLRP3 and AIM2, and noncanonical inflammasomes may be involved in the pathogenesis and development of periapical periodontitis." (PMID 34177950, 2021).
aseptic meningitis (8 papers, 2013 to 2025). Inflammation of the membranes surrounding the brain and spinal cord without a bacterial pathogen. "We observed severe CNS manifestations including recurrent aseptic meningitis/meningoencephalitis and optic neuritis as well as cerebral vasculitis in several patients w/o MS, most of them harboring the Q703K NLRP3 variant." (PMID 32563262, 2020). "Recurrent aseptic meningitis was seen in patients with FMF and two cases of CAPS carrying NLRP3 mutations." (PMID 38632524, 2024). "Moreover, only one MEFV mutation was found in a subset of FMF patients, although FMF is traditionally considered an autosomal recessive disease, and both NLRP3-related diseases and FMF are IL-1β activation disorders, which may cause aseptic meningitis." (PMID 23432807, 2013). "We emphasize the importance of recognizing NLRP3-AID based on clinical manifestations, particularly in cases of recurrent aseptic meningitis, fever, and rashes, beyond relying solely on genetic testing." (PMID 40852416, 2025). "We recommend considering NLRP3-AID in infants with recurrent fever, rash, and aseptic meningitis." (PMID 40852416, 2025).